SMO (smoothened, frizzled class receptor)
Diseases named in the same sentence as SMO in open-access papers (continued):
Sharing a sentence is not in itself a finding about the gene and the disease.
cancer (continued). "SMO-related inhibitors could have anti-cancer ability in vitro or in vivo, even in clinical trials." (PMID 32962123, 2020). "Moreover, this study may prove valuable for future research aimed at producing therapeutic downregulation of SMO expression in cancer cells." (PMID 32784501, 2020). "SMO inhibitors could inhibit the proliferation of cancer cells." (PMID 31979397, 2020). "In addition, SMO inhibitors serve as another strategy against cancer stem cells." (PMID 32962123, 2020). "Because the inhibition of the Hh pathway in CSCs may sensitize these cells to cytotoxic drugs and radiation, the therapeutic relevance of such inhibition may extend beyond those cancers that dysregulate SMO or other components of the pathway in bulk of the tumor." (PMID 31539380, 2019). "High SMO protein levels were significantly associated with female patients (p = 0.001), patients grouped into the N1-2 category of UICC classification (p = 0.001), and patients in Stage II-III of the American joint committee for cancer (AJCC) classification (p = 0.003)." (PMID 31417657, 2019). "Hence, PI3Kα/mTOR targeting might be a promising strategy for HH-driven cancers that are resistant to SMO inhibitors." (PMID 31492956, 2019). "An alternative, intriguing hypothesis points to the existence of noncanonical, compensatory signal pathways that drive SMO-independent GLI1 activation in cancer, thus bypassing the inhibitory activity of SMO antagonists and hence contributing to the acquisition of resistance." (PMID 30558232, 2018). "Upregulation of SMO and Hh coreceptors [growth arrest-specific protein 1 (GAS1), brother of CDO (BOC), and cell adhesion molecule-related/down-regulated by oncogenes (CDON)] has been, for example, observed in cancer-associated fibroblasts derived from pancreatic adenocarcinomas." (PMID 29695137, 2018). "When activated by SMO or other signaling, GLI1 can be translocated into nucleus and orchestrate expression of its downstream oncogenes, leading to cancer development and progression." (PMID 41323789, 2025). "Previous antitumor studies have focused on SMO targets upstream of the Hh pathway; however, in recent years, GLI has been found to play a more important role than SMO in cancer development (Stecca and Ruiz i Altaba, 2010)." (PMID 40255562, 2025). "With respect to inhibition of the HH pathway, most drugs inhibit the HH target SMO, with several receiving FDA approval as anti-cancer agents." (PMID 38612911, 2024). "Vismodegib (GDC-0449) is a small molecule antagonist of SMO and was the first FDA approved HH pathway inhibitor for cancer." (PMID 38612911, 2024). "LDE-225 (Erismodegib/Sonidegib/Odomzo), a Cyclopamine derivative, effectively induces cell cycle arrest and apoptosis across various cancers, including GBM, by antagonising SMO and reducing GLI protein expression, validated in mouse models." (PMID 39568072, 2024). "The Hh pathway has served as a promising therapeutic target for various cancers, with SHH, SMO, and GLI validated as targetable factors." (PMID 38909089, 2024). "In pathological situations such as cancer, the SHH ligand binds to the PTCH receptor to release SMO and stimulate the translocation of GLI1 into the nucleus in a canonical SMO-dependent way." (PMID 37149646, 2023). "In our study, cotreatment FAK inhibitor with SMO inhibitor, VS‐4718 with GDC‐0449, exhibited the superior inhibition against cancer development, invasion, and stemness activity than each agent alone." (PMID 37846367, 2023). "Smoothened (SMO), which is essential to the sonic hedgehog homolog (SHH) signaling pathway, has been revealed to play a crucial role in the cellular behavior of cancer stem cells." (PMID 36865478, 2023).
cancer (continued). "Furthermore, these results may explain the failure of colon cancer trials using HH pathway inhibitors, given that it is plausible that the pro-inflammatory responses to SMO-targeting may contribute to the acceleration of cancer progression, forcing the termination of the clinical studies." (PMID 36674836, 2023). "Several SMO inhibitors, such as LEQ-506, TAK-441, itraconazole, and taladegib were discovered as SMO antagonists that enhance cancer treatment efficacy." (PMID 38020914, 2023). "SMO inhibitors have transformed the treatment paradigm for BCC, and studies are in progress to expand their use in other types of cancer." (PMID 35163655, 2022). "Sonidegib (Erismodegib, LDE225, Odomzo) is the second SMO inhibitor approved for treatment of advanced BCC and is currently being investigated for treatment of other cancers." (PMID 35990601, 2022). "Pro-oncogenic proteins, such as Src, SMO and c-MET, localize in lipid rafts and initiate signaling transduction, indicating potential involvement of lipid rafts in cancer progression." (PMID 35303882, 2022). "summarized the known target genes of GLI1 in human cancers, including components of the Hh signaling pathway (PTCH, SHH, and SMO)." (PMID 35785194, 2022). "We further evaluated the survival differences between the SMO_MUT and SMO_WT groups in two non-ICI-treated pan-cancer cohorts to explore whether the OS advantage can be attributed to ICI treatment in patients carrying SMO mutations or was just simply due to its general prognostic impact." (PMID 36405701, 2022). "Numerous studies accounted for the involvement of various noncanonical mechanisms in the over-activation of GLI proteins, which explained the ineffectiveness of SMO and upstream inhibitors in the treatment of certain GLI-overexpressing cancers." (PMID 34572373, 2021). "Increased Shh expression can promote the autocrine Hh-GLI pathway activation of cancer cells and stromal cells through repression of PTCH1 and increase SMO activation, thus leading to transcriptional activation of Hh target genes and carcinogenesis." (PMID 34572373, 2021). "In the next part, we focused on the SMO-dependent and -independent mechanisms by which GLI is activated and their relevance to cancer hallmarks." (PMID 34572373, 2021). "SMO inhibitors such as vismodegib, IPI-926, and sonidegib showed high efficacy in cancer types like basal cell carcinoma or medulloblastoma which often harbor activating mutations in the HH pathway." (PMID 34333666, 2021). "From a wide range of Hh inhibitors that were developed and tested preclinically, SMO and GLI inhibitors have shown the most promise due to their improved efficacy in both in vitro and in vivo cancer models." (PMID 34572373, 2021). "Expression levels of the HH pathway genes, the HH signaling receptors PTCH and SMO, and the target transcription factors GLI2 and GLI3, varied significantly among the cancer cell lines." (PMID 32784501, 2020). "In the current study, we have developed a qRT-PCR method to accurately determine the expression levels of SMO, PTCH1, GLI1, GLI2, and GLI3 in a panel of cancer cell lines." (PMID 32784501, 2020). "Drug resistance develops following SHH/SMO/GLI signaling, upregulating drug-transport-pump expression in cancer stem cells." (PMID 32962123, 2020). "SUFU mutations have been identified to activate aberrant HH pathway in cancer HH ligands to bind to PTCH, and PTCH can thereby release the inhibition of SMO." (PMID 32962123, 2020). "In colon tissue, the ratio of SMO and GLI protein expression is increased significantly in cancer and adenoma tissue compared with normal colon tissue." (PMID 32962123, 2020). "After looking through papers, only 4 genes of these prognostic markers have been verified to be relavant with according cancers, including CCL4 in COAD, CACNA2D3 and SMO in ESCA, and IL23R in LUAD." (PMID 31888612, 2019).
cancer (continued). "Recently, FOXC1 has been shown to activate GLI2 in a SMO independent SHH pathway, which partly explains the aggressiveness of BLBC cell and adds a new role for FOXC1 in cancer cell stemness." (PMID 29487724, 2018). "However, secondary resistance mutations in SMO or genetic alterations of downstream HH target genes have been identified only in a subset of resistant MB and BCC tumors and failed to explain the emergence of resistance towards SMO inhibitors in other types of cancer." (PMID 30558232, 2018). "In other cancer cells, many genes have been identified as miR-338-3p targets, including ADAM17, PREX2a, ZEB2, Sox4, SMO, MACC1, and IRS2." (PMID 29618948, 2018). "Moreover, SMO antagonists are not effective in cancers where HH activation is due to mutations of pathway components downstream of SMO, or in the case of noncanonical, SMO-independent activation of the GLI transcription factors, the final mediators of HH signaling." (PMID 30558232, 2018). "In this scenario, the pathway intermediates SMO and GLI-1 would contribute to the autonomous maintenance of epithelial malignant neoplasms." (PMID 28948003, 2017). "Secondly, we demonstrated that CycT and another SMO inhibitor SANT1, like glutamine depletion, suppress the rates of oxygen consumption and the rates of cancer cell proliferation." (PMID 26911235, 2016). "In several different assays, TAK-441 was shown to have equal affinity for wild-type and mutated SMO, while Vismodegib and cyclopamine showed reduced affinity for the D473H mutant suggesting that TAK-441 may be clinically relevant to treating Vismodegib-resistant, Shh pathway-driven cancers." (PMID 26891329, 2016). "When Gli1 was activated by mTOR signalling through the SMO-dependent canonical pathway, S6K1-mediated Gli1 phosphorylation prevents Gli1 from SuFu-mediated inhibition in the cancer cells." (PMID 26218750, 2015). "Recently, studies in several human cancers have shown that GLI1 expression is independent from HH ligand and canonical intracellular signaling through PTCH and SMO." (PMID 26633513, 2015). "HH signaling proteins, PTCH, SMO, and GLI2 seem to have prognostic value in cases with residual carcinoma, local recurrences, and for GLI2 distant relapses." (PMID 26588701, 2015). "Small molecule inhibitors of SMO upstream of GLI have probed the canonical, HH-SMO-GLI axis in preclinical models and in human cancers." (PMID 24962990, 2014). "Small molecule inhibitors of SMO upstream of GLI have been investigated in preclinical models, and in the treatment of various types of cancers in humans." (PMID 23097684, 2012). "On the other hand, it has been shown that cancer cells can also become resistant to Hh pathway inhibitors by losing cilia to render them independent of SMO signaling." (PMID 40301543, 2025). "However, they occurred independently of tissue invasion (perineural, lymphovascular, fat, bone, muscle, and mucous acini) and proteins related to the HH pathway (SHH, IHH, SMO, and GLI‐1), which contributed to the morphogenesis of this rare cancer." (PMID 40930949, 2025). "SMO correlated with mitotic count in BCC but not in SCC or SEB, whereas higher SMO consistently paralleled a higher Ki67 index across all three carcinomas." (PMID 40542075, 2025). "Cancer patients with Hedgehog pathway overactivation develop drug resistance to FDA-approved SMO inhibitors due to the compensatory SMO-independent, non-canonical activation of GLI1/2." (PMID 37950038, 2024). "In addition to canonical GLI activation through the HH–PTCH–SMO pathway, which is commonly observed in normal cells, accumulating evidence indicates the existence of SMO-independent GLI function induction in cancer." (PMID 38020914, 2023). "The existence of noncanonical HH is extremely relevant in cancer cells, as it can partly explain constitutive or acquired resistance to SMO inhibitors." (PMID 36769284, 2023).
cancer (continued). "Moreover, in human cancers, genetic alterations of HH-related genes such as PTCH1, SMO, and SUFU significantly influence cilia-dependent tumorigenesis." (PMID 37510333, 2023). "SOX2-mediated GLI activation is best characterized in SHH-MB, where a SOX2-enriched cancer cell cluster harbors noncanonical GLI activation to render them resistant to SMO inhibition." (PMID 36556332, 2022). "In B-cell ALL, cancer stem cells that were treated with a Smo inhibitor showed decreased self-renewal potential, a result mirrored by the subset of GLI1 rich T-cells when they were treated with either a GLI or SMO inhibitor." (PMID 36091167, 2022). "The activated SMO further leads to activation of Gli transcription factors for biological functions and aberrant SHH signaling pathway plays driver roles in several types of cancers." (PMID 35419951, 2022). "In addition, SMO and GLI inhibitors have been shown to exert an anti-cancer activity both in vitro and in vivo on different types of cancer." (PMID 34956733, 2021). "The specific expression pattern and higher stability implied that circ-SMO maybe an ideal biomarker for human GBM, while further exploration is clearly warranted in other types of cancers." (PMID 33446260, 2021). "Thus, therapeutic strategies for SHH-pathway-dependent cancers primarily aim at inhibiting the components of the SHH pathway, including the SHH ligand itself as well as SMO and GLI proteins." (PMID 34436033, 2021). "Hedgehog signaling pathway effectors such as SMO and GLI, are essential for cancer progression." (PMID 34445421, 2021). "Therefore, several components of the HH pathway are under investigation for targeted cancer therapy, particularly GLI1 and SMO." (PMID 32957513, 2020). "The absence of SMO expression in seven cell lines derived from breast (5 of 9), stomach (1 of 1), and colon (1 of 1) cancer tissues was correlated with a high level of gene methylation." (PMID 32784501, 2020). "Despite a strong link between SMO expression, HH pathway activity, and cancer development, the basis for SMO gene regulation has not been well characterized." (PMID 32784501, 2020). "In addition to the experimental R/K6.32 to alanine mutants, we have also performed mG BRET experiments using the naturally occurring cancer mutants FZD6 R416Q6.32 and SMO R455H6.32, as well as FZD6 W493L7.55 and SMO W539L7.55." (PMID 30737406, 2019). "Cumulative data indicate that SMO-independent hedgehog signaling, namely non-canonical hedgehog signaling, plays an essential role in cancer through activation of GLI as the output for numerous other oncogenic pathway." (PMID 29515801, 2018). "Several clinical trials with SMO antagonists led to negative results due to low selectivity on cancer stem cells (CSCs), poor pharmacokinetic properties, and the occurrence of mechanisms of non-canonical HH pathway activation downstream of SMO13,14." (PMID 29396391, 2018). "The mTOR target S6 (a serine/threonine kinase) has previously been shown to activate GLI1 in multiple cancer types, independent of SMO, indicating a crosstalk between the PI3K/AKT/mTOR- and Hh pathways." (PMID 28789624, 2017). "We further demonstrated and SMO antagonist BMS833923 was not able to sensitize cancer cells to 5-FU (data not shown here), suggesting that up-regulation of GLI1 was not caused by canonical Hh signaling." (PMID 28413604, 2017). "The protein levels of Gli1, Ptch1, and SMO were examined after itraconazole treatment, and signals decayed after peak in endothelial cells, which was not shown in cancer cell." (PMID 28747628, 2017). "Therefore, several components of the Shh pathway (Shh, SMO, and GLI1/2) are viable therapeutic targets for anti-cancer therapies." (PMID 26891329, 2016). "This is a more efficient strategy for interrupting Hh signaling considering the presence of SMO mutations and of the “non-canonical” mechanism of GLI protein activation in cancer." (PMID 26843616, 2016).
cancer (continued). "Genetic alterations, including loss of PTCH function, constitutively active SMO, and amplification of GLI1/GLI2 have been reported to activate downstream Hedgehog signaling independent of ligands in various cancers." (PMID 26936993, 2016). "A recent study has shown that the mTORC1 substrate, S6K1, directly regulates hedgehog signalling in cancer cells by interacting with and phosphorylating Gli1, but not Gli2 via a SMO-independent mechanism." (PMID 27039827, 2016). "Additional SMO inhibitors are currently available and many, including vismodegib (GDC-0449), sonidegib (LDE-225), BMS-833923, PF-04449913 and LY2940680 are being investigated in clinical trials in a number of advanced cancers (Ref." (PMID 25660620, 2015). "We have shown that SMO inhibitor cyclopamine and GLI inhibitor GANT61 are both able to down regulate SOX18 expression in HeLa cells, opening a new field of potential manipulation with this gene expression in cancer." (PMID 26588701, 2015). "Equally important is to differentiate cancers with canonical and non-canonical HH pathway activation, and among the latter SMO-dependent from SMO-independent cancers." (PMID 25660620, 2015). "Moreover, genes in the WNT, SHH, and BMP pathways such as WNT5A, FZD7, and FZD5, SHH, SMO, and GLI2 as well as BMP4 were likewise among the upregulated genes and were included in pathway of cancer gene set." (PMID 26998479, 2015). "Aberrant activation of HH signaling in human cancers could result from genetic alterations in pathway components, including PTCH1, SMO, SUFU and GLI1." (PMID 23826113, 2013). "Moreover, the role of few important proteins has been identified in this pathway, such as PTCH1, SMO, GLI etc., which are mainly responsible for the malfunctioning of this pathway in various types of cancers." (PMID 23935937, 2013). "Indeed, we here show that PDGFRα and essential components of the Hh pathway, including SMO, PTCH1 and GLI2, localize to primary cilia of wt OSE cells and that cancer OSE cells display increased basal expression of Hh responsive genes." (PMID 23351307, 2012). "Cancers such as melanoma that activate both canonical and non-canonical Hh /Gli signaling pathways may not respond well to SMO interference in terms of preventing Hh signaling." (PMID 37240209, 2023). "The HH signaling pathway may also be activated via non-canonical (SMO-independent) HH signaling mechanisms, which may also lead to cancer development." (PMID 36986819, 2023). "Therefore, we will focus on Hh ligand-independent, SMO-independent activation of GLI transcription factors in our discussion of noncanonical activity of the pathway in cancers." (PMID 36010600, 2022). "However, unlike other cancers, the response to G-protein-coupled receptor smoothened (SMO)/Hh inhibitors is poor, mainly attributable to the lack of markers for patient stratification." (PMID 36358635, 2022). "Since ligand- and SMO-independent GLI activation has been documented in AML and MDS, novel approaches capable of directly targeting GLI may expand the utility of HH pathway inhibition in these diseases as well as other cancers." (PMID 34638372, 2021). "Thus, as SMO mutants can constitutively activate Hh signaling by GLI activation to promote cancer cell survival, targeting GLI may serve as a promising second-line therapy for the treatment of SMO-inhibitor-resistant tumors." (PMID 34572373, 2021). "An investigational SMO inhibitor, taladegib, has demonstrated a potent inhibitory effect on SMO D473H mutant and showed promising antitumor efficacy in Hh treatment-naïve and previously Hh-treated BCC patients, showing promise as second-line therapy for SMO-inhibitor resistant cancers." (PMID 34572373, 2021).